IDH1 (isocitrate dehydrogenase (NADP(+)) 1)
Diseases named in the same sentence as IDH1 in open-access papers (continued):
Sharing a sentence is not in itself a finding about the gene and the disease.
glioma (continued). "In our study, glioma with IDH1 mutation showed a higher MGMT promoter methylation compared to glioma without this mutation (55.6% vs. 18%, p=0.032)." (PMID 32856857, 2020). "However, little is known about the nutrient requirements of isocitrate dehydrogenase 1 (IDH1) mutant gliomas." (PMID 32575619, 2020). "This study showed that IDH1 mutations were found more commonly in grades II and III of glioma." (PMID 32856857, 2020). "In terms of molecular pathology, the risk score was found to be much higher in IDH1 wild-type and 1p/19q-non-codeletion gliomas." (PMID 33230136, 2020). "Qualitative MRI features have been shown to correlate with IDH1 genotypes in high grade gliomas." (PMID 33121211, 2020). "Typically, millimolar concentrations of 2HG are found in gliomas bearing IDH1/2 mutants." (PMID 31847543, 2020). "Clinical translation of AC/DC and MRSI is demonstrated in a patient with mutant-IDH1 glioma where it enables imaging of D-2-hydroxyglutarate oncometabolite with a 2.8-fold increase in contrast-to-noise ratio at higher resolution and more brain coverage compared to previous 7 T studies." (PMID 32929121, 2020). "Furthermore, mutant IDH1 expression can be induced following NSCs differentiation into alternative putative cells of origin of glioma." (PMID 32946483, 2020). "The results of all these investigations, taken together, validate that invariably better survival in glioma patients with respect to IDH1 mutant tumors can mainly be attributed to less aggressive oncogenic mode and is less likely due to outcome of treatment by chemotherapy." (PMID 33552543, 2020). "Also, there are only very few high-frequency mutated driver genes like IDH1/IDH2 and promoter of TERT discovered in gliomas." (PMID 32328184, 2020). "Tumors with IDH1 or IDH2 mutations have distinctive genetic and clinical features, and patients with such tumors have a longer overall survival time compared to patients with wild-type gliomas." (PMID 32013066, 2020). "However, for genes that were mutated in lower-grade glioma, such as IDH1, TMB was lower in the IDH1 mutant group than in the IDH1 wild-type group." (PMID 32164609, 2020). "The authors suggested that the result indicated that the proliferation rate of IDH1 mutated glioma is not different from that of IDH1 wild type GBM." (PMID 32856857, 2020). "In addition, the isocitrate dehydrogenase 1 (IDH1) gene mutation is considered a specific marker for glioma, and the radiomics method has been developed to reveal IDH1 status for patients with glioma." (PMID 32185138, 2020). "This kind of vast metabolic rewiring occurs to preserve TCA-cycle activity in IDH1-mutant gliomas." (PMID 32397535, 2020). "MRS detected elevated 2-HG levels in gliomas with IDH1 mutations compared with those without the mutation (p = 0.003)." (PMID 31901171, 2020). "These alterations, resulting from IDH1 and IDH2 mutations, could contribute to gliomagenesis through modifying epigenetic control and potentially the fates of stem or glioma progenitor cells." (PMID 32993063, 2020). "The decision tree classifier predicted the highest possibility rate of short post-surgical survival time for the glioma patients with the combination of IDH1 wild-type genotype, lower miR-181d tumoral expression, higher miR-181b tumoral expression, and weaker tumor related symptoms." (PMID 33050332, 2020). "We only compared the tracer uptakes in grade II and III gliomas with IDH1 mutation and grade III and IV gliomas without IDH1 mutation." (PMID 32382870, 2020). "Furthermore, IDH1 wild-type gliomas more frequently had lower CASC2 and higher miR-21 expression (p = 0.037 and p < 0.0001, respectively)." (PMID 33120918, 2020). "The remaining cluster (methylation cluster PA-like) consisted largely of lower grade gliomas without detectable IDH1 or H3 mutations." (PMID 32555164, 2020).
glioma (continued). "Attempted maximum safe surgical resection may be more justified in patients with IDH1-mutant gliomas, whilst a more limited resection may be more appropriate for IDH1-wildtype gliomas." (PMID 33302429, 2020). "IDH1 wild-type lower-grade glioma was a group of patients with high heterogeneity." (PMID 33229627, 2020). "Tumor-associated epilepsy and the IDH-1 mutation did not affect hippocampal volume in glioma patients." (PMID 32507763, 2020). "The survival prognosis of tumor or glioma patients with R132H mutation was better than the cases with R132H non-mutation of the IDH1 gene (P < 0.001)." (PMID 33308219, 2020). "Interestingly, we found both IDH1/2 genes mostly prevalent in two subtypes of gliomas: astrocytoma and oligodendrogliomas with a frequency of 71.4 and 85.7% for IDH1 and 14.28 and 28.5% for IDH2, respectively." (PMID 33552543, 2020). "Frequency and nature of IDH1 and IDH2 mutations in glioma patients." (PMID 33552543, 2020). "Taken together, the sPD-L1 level increased after RT, suggesting that RT combined with immune checkpoint inhibitors might be better than RT alone for glioma patients, especially for patients with IDH-1 MUT." (PMID 33224142, 2020). "For example, all four IDH1-wt glioblastoma GSCs with BRAF hotspot mutations (V600E and D594H) were classified into the E&F-independent group, although BRAF alterations are rarely observed in adult HGG or other diffusely infiltrating gliomas (2–5%)." (PMID 32120790, 2020). "Mutations in IDH1 and IDH2 are observed in less than 5% of pediatric high-grade gliomas." (PMID 32977537, 2020). "For example, the rapid determination of IDH1 status in a patient with a glioma diagnosis could inform intra-operative decision-making between alternative surgical strategies." (PMID 33302429, 2020). "Mutations in the IDH1 and IDH2 genes usually occur in low-grade gliomas as well as secondary GBMs." (PMID 33237934, 2020). "Moreover, the PARP9 expression level increased with glioma grade and was associated with clinicopathological parameters (age, vital status, tumor status, histological type, KPS, and IDH1 status)." (PMID 32678519, 2020). "Gliomas must be now classified based on the presence or absence of isocitrate dehydrogenase 1/2 (IDH1/2) mutations, as this is a strong prognosis indicator." (PMID 33147752, 2020). "The impact of better survival by chemotherapy using TMZ irrespective of IDH1 mutation status was observed in the glioma cases." (PMID 33552543, 2020). "IDH-1 status has been considered an effective factor in predicting OS of glioma patients." (PMID 32642801, 2020). "Because available studies indicated that isocitrate dehydrogenase 1 (IDH1) mutants showed better prognosis compared to IDH-wildtype glioma patients at different WHO grades, therefore in the next step we analyzed proteasome activity depending on the mutation of the IDH1 gene." (PMID 32886667, 2020). "We are now inspired to investigate, whether the differential expression of the pre-promoter region of the IGS correlates with the mutation of IDH1 gene, or whether it can serve as additional biomarker of grade III glioma." (PMID 32731436, 2020). "They concluded that mutant IDH1 can play an anti-tumor role in glioma." (PMID 33221817, 2020). "IDH1/2 are commonly mutated genes in grade II and grade III gliomas, with incidences of >75%13,14." (PMID 32576825, 2020). "Hitherto, there is no study focusing on the combined estimation of glioma IDH1 mutation and VEGF expression with histogram analysis of DCE-MRI." (PMID 33425744, 2020). "Both MET-PET/CT and FLT-PET/CT were able to distinguish between grade II and III gliomas in IDH1-mutant tumours (P = 0.002 and P < 0.001, respectively), but only FLT-PET/CT was able to distinguish between grade III and IV gliomas in IDH1-wildtype tumours (P = 0.029)." (PMID 32382870, 2020). "Patients with IDH1 mutated, age ≤ 40, KPS scores > 80 before operation and low-grade glioma may have a longer life and better prognosis." (PMID 32582544, 2020).
glioma (continued). "And it is found that IDH1 mutations and IDH2 mutations are mutually exclusive in gliomas." (PMID 32280672, 2020). "Hypoxia microenvironment promotes glioma cells aggressive phenotype by upregulating hypoxia-inducible factor (HIF) family.HIF1A is highly expressed in glioblastoma and significantly correlated with IDH1/2 mutation." (PMID 32677981, 2020). "The mRNA expression-based stemness index (mRNAsi) was significantly associated with the glioma histologic grade, isocitrate dehydrogenase 1 (IDH1) mutation and overall survival of glioma patients by the nonparametric test and Kaplan–Meier survival analysis." (PMID 32725165, 2020). "However, their value in differentiating low-grade vs. high-grade glioma needs further validation due to the high uptake in ODs, which is as high as that for high grade IDH1-wildtype gliomas." (PMID 32698507, 2020). "This retrospective study included patients with glioma with known IDH1 status and preoperative MRI." (PMID 33121211, 2020). "In general, overall survival was better in cases with IDH1 R132H mutation in all glioma cases and both AA and GBM although the P values were not statistically significant (P > 0.05)." (PMID 33282092, 2020). "Reprogramming of glioma cells derived from patients and established isogenic clones is an alternative way to generate disease models for glioma—with or without IDH1 mutations." (PMID 33221817, 2020). "IDH1 mutant glioma was more likely to cross the midline to the other hemisphere (p = 0.001)." (PMID 32582544, 2020). "Here we provide evidence suggesting that glioma subgroups with and without IDH1 mutations use different TMM and describe a new pathway linking the IDH1R132H mutations to ALT." (PMID 31960234, 2020). "The prognosis of IDH1-mutant glioma is significantly better than that of wild-type glioma." (PMID 33163535, 2020). "These overexpression systems do not reflect the oncogenic properties of the heterozygous IDH1 mutation present in patient tumor cells and do not offer the opportunity to analyze cellular origin of gliomas." (PMID 32946483, 2020). "The IDH1 and 1p/19q status is related to the prognosis of gliomas." (PMID 33299501, 2020). "There was a significant difference in age between IDH1-mutant and IDH1 wild-type glioma patients." (PMID 33163535, 2020). "Metabolism-related genes have been previously reported to have a differential expression in this model compared to their wild type (WT) counterpart; indeed, IDH1wt and IDH1mut gliomas are biologically distinct tumors with solid differences in their molecular profiles beyond the IDH1 status." (PMID 32575619, 2020). "Isocitrate dehydrogenase 1 (IDH1) is a vital marker for the molecular classification of glioma." (PMID 32819307, 2020). "The role of nonimaging biomarkers in gliomas and GBMs is well known, i.e., IDH1 mutation and methylguanine-DNA methyltransferase (MGMT) promoter methylation." (PMID 33072586, 2020). "In addition, frequently observed mutations to EGFR (27%), IDH1 (20%), PTEN (18%), and MUC16 (16%) were present in gliomas with low TOX expression (n = 158)." (PMID 32762688, 2020). "IDH1 and IDH2 have been reported to be mutated in 70% of grade II and III gliomas and glioblastomas, as well as in angio-immunoblastic T-cell lymphomas, acute myeloid leukemia (AML) and other common cancer types, such as thyroid, colorectal and prostate cancers." (PMID 32548570, 2020). "Patients with IDH1 mutated, age ≤ 40, KPS scores > 80 before operation and low-grade glioma may have a longer life and a better prognosis." (PMID 32582544, 2020).
glioma (continued). "Knowledge of the IDH1 status would be beneficial, as maximum resection may be preferred in patients with IDH1-mutant gliomas, whilst a more limited resection can be best for IDH1-wildtype gliomas." (PMID 33302429, 2020). "The isocitrate dehydrogenase gene 1 and 2 (IDH1/IDH2) mutational status and the hypermethylator phenotype [glioma CpG island methylator phenotype (G‐CIMP)], both characteristic of secondary GBMs and associated with longer survival times, were then considered to improve the TCGA classification." (PMID 31701625, 2020). "The concentration of D2HG in glioma cells carrying IDH1-R132H is usually between 10 and 30 mM24." (PMID 33221817, 2020). "Recently, Gary and colleagues found that IDH1 mutations could suppress STAT1 signaling and CD8+ T cell accumulation to promote the immune evasion ability of gliomas." (PMID 32508015, 2020). "Besides, we found that EGFR-positive expression was more common in the middle-age group, and the EGFR expression in IDH1-mut gliomas was more apparent." (PMID 32819307, 2020). "In particular, the in-vivo longitudinal measurement of intratumoral 2HG levels could be critical to assess the pharmacodynamics of molecular drugs and ultimately the efficacy of targeted treatment, such as mutant-IDH1 inhibitors in glioma patients." (PMID 33081358, 2020). "Next, we analyzed FASN expression in a panel of glioma cell lines, including the glioma stem-like (GSC) cell lines BT112, BT145, NCH421k, and GS-8, which are IDH1-wildtype, the IDH1-mutated lines NCH1681, NCH551b, and BT142, and the serum-cultured glioblastoma cell line U87." (PMID 32178271, 2020). "Our experiments with patient samples also showed reduced levels of ATP in IDH1 mutant gliomas." (PMID 31278288, 2019). "GPIHBP1 expression in glioma capillaries did not appear to correlate with glioma grade, 1p/19q co-deletions, or IDH1 mutations." (PMID 31169500, 2019). "Both total and phosphorylated STAT1 protein was shown to be reduced in IDH1 mutant gliomas, and knockdown of STAT1 in wildtype IDH1 tumors resulted in reduced expression of these chemokines, suggesting that R-2-HG can potentially abrogate cytokine signaling through this pathway." (PMID 31781488, 2019). "Introduction of IDH1-mut into transgenic mouse gliomas with different genetic background, expressing platelet-derived growth factor alpha (PDGFα), shp53, or Ink4a/Arf+/+ and Ink4a/Arf+/−, demonstrated significantly shorter survival compared to mice with IDH1-wt tumors." (PMID 30857299, 2019). "In glioma, mutations in IDH1 are considered ancestral, driving gliomagenesis but not necessarily glioma progression." (PMID 31139406, 2019). "Thereby, it has been suggested that glioma cells expressing mutant IDH1 have a diminished antioxidant capacity and therefore may experience a subsequent loss of cytoprotection under conditions of oxidative stress." (PMID 31242696, 2019). "IDH1/2 somatic mutations are associated with lower normalized mean diffusion kurtosis, increased ZEB1 expression in lower-grade gliomas, preoperative seizures in gliomas, CpG methylator phenotype (CIMP), global hypermethylation, younger age, secondary glioblastoma, and increased overall survival." (PMID 29556922, 2019). "Although β-oxidation has been thought to be less efficient in the brain compared with other tissues, β-oxidation may be more efficient in IDH1 normal than IDH1 mutant gliomas." (PMID 31278288, 2019).
glioma (continued). "In accordance with this preclinical data, analysis of surgically resected tumors from patients with IDH1-mutant gliomas indicate decreased levels of 2-HG following pretreatment with either AG-881 or AG-120, indicating that both inhibitors penetrate into the CNS (ClinicalTrials.gov NCT03343197)." (PMID 31652645, 2019). "Our recent work revealed that the expression of lncRNA SNHG18 was related to the clinical tumor grade and showed a negative correlation with mutations of IDH1 in glioma." (PMID 31798634, 2019). "Pathology was again consistent with a high-grade IDH1-mutant glioma." (PMID 30738431, 2019). "Inhibitor of mutant IDH1 (AGI-5198) impaired the growth of IDH1-mutant but not IDH1-wild-type glioma cells by increasing the expression of genes associated with gliogenic differentiation." (PMID 31450721, 2019). "When LGG patients in the CGGA dataset were classified into 4 groups according to the WHO grade and IDH1 mutation status, the expression levels of PSAT1 were highest in the group of grade II gliomas with IDH1 mutations, which was supposed to be the group with the best prognosis in LGGs." (PMID 31861486, 2019). "As IDH1-wt gliomas exhibit increased PD-L1 expression and greater TIL infiltration, those tumors are considered to be more immunologically active and more susceptible to immunomodulatory therapy against PD-1/PD-1L than IDH-mut gliomas." (PMID 30857299, 2019). "Similarly, glutamine-derived α-ketoglutarate can also regulate the epigenome, as evidenced in IDH1/2 mutant gliomas, as it serves as a co-substrate for a class of dioxygenase enzymes." (PMID 31652923, 2019). "In 2008, whole-genome analysis led to the discovery of recurrent mutations of IDH1 in secondary (those progressing from lower grade gliomas) rather than in primary GBMs." (PMID 31138764, 2019). "All these results suggest that high-grade glioma patients were older, were not likely with IDH1 mutation and exhibited poor survival." (PMID 32047515, 2019). "The IDH1/2 mutations can produce a high level of 2-HG to inhibit the differentiation of glioma stem cells, upregulate the formation of the tumor microenvironment, and produce a high level of HIF-1α to promote the invasion of glioma." (PMID 31263678, 2019). "A robust and durable activity of DNMTi on tumor growth inhibition described by our group is that DAC-treated glioma cells harboring IDH1 mutation and 1p19q co-deletion remain viable, but without evidence of tumor growth onset in mice for 55 days." (PMID 31652645, 2019). "This indicates that, unlike the observations in gliomas, IDH1 or IDH2 mutations in chondrosarcoma do not correlate with radiosensitivity." (PMID 31160965, 2019). "Immunopositivity for IDH1 R132H is sufficient to classify a glioma as “IDH-mutant”." (PMID 30967140, 2019). "In future studies, we will develop an ensemble model that integrates multiple gene signatures designed for different subgroups of glioma patients stratified by molecular subtypes or major genomic mutations in IDH1, CIMP, EGFR and PTEN in glioma cohorts to further improve the predictive accuracy." (PMID 31097021, 2019). "In the IDH1-mutant glioma model, AGI-5198 induces the expression of genes related to the differentiation of astrocytes and oligodendrocytes and reduces the inhibitory histones at the promoters of these genes, thereby promoting the differentiation of glioma cells." (PMID 31263678, 2019). "It suppressed the production of 2-HG in a dose-dependent manner and significantly inhibited growth of anaplastic oligodendroglioma cells harboring heterozygous IDH1/R132H mutation without influence on IDH1-wt patient-derived glioma cells." (PMID 30857299, 2019). "Subsequently, the German National Cancer Center launched a Phase I trial, IDH1 Peptide Vaccine in IDH1 R132H Mutant III-IV Glioma (NOA-16) (NCT02454634), and Duke University also launched a clinical trial, called “IDH1 Peptide Vaccine for Recurrent Grade II Glioma (RESIST)” (NCT02193347)." (PMID 31263678, 2019).